ALB (albumin)
Diseases named in the same sentence as ALB in open-access papers (continued):
Sharing a sentence is not in itself a finding about the gene and the disease.
malnutrition (continued). "Particularly, the inverse correlation between albumin and age, possibly indicating malnutrition, observed in the present study, along with the increased mortality in older adults as shown in this study and elsewhere, suggest an obscure contribution of low albumin level to the lactate/albumin ratio." (PMID 39685564, 2024). "Serum albumin levels are now considered an important marker in the measurement of malnutrition." (PMID 38732604, 2024). "However, elevated NT-proBNP can result not only from cardiac causes but also from impaired renal function, atrial fibrillation, older age, malnutrition (low albumin), or high levels of C-reactive-protein." (PMID 38191350, 2024). "Furthermore, a high PAR level indicates a low albumin count, suggesting malnutrition and high inflammation and predicting poor clinical outcomes." (PMID 39097679, 2024). "Finally, postoperative malnutrition exacerbates albumin depletion and impedes wound healing and recovery, thereby amplifying infection susceptibility." (PMID 39496632, 2024). "Despite the widespread use in ischemic stroke, cancer, and malnutrition, the predictive ability of serum albumin to globulin ratio (A/G) among patients suffering from aneurysmal subarachnoid hemorrhage (aSAH) remains unknown." (PMID 39539653, 2024). "Serum albumin has emerged as one of the most commonly used clinically relevant indicators of malnutrition due to its short half-life, with values of <3.5 g/dL frequently being defined as malnutrition in the literature." (PMID 38541767, 2024). "Recent studies highlight that amino acid profiles, particularly levels of tyrosine (Tyr), tryptophan (Trp), and phenylalanine (Phe), can serve as potential biomarkers for malnutrition, offering more accurate assessments compared to traditional markers like BMI and serum albumin." (PMID 39125381, 2024). "GNRI is the superior nutritional index in areas including specificity, diagnostic power, and predictability of postoperative complications and should be considered as an adjuvant screening tool for malnutrition in geriatric patients in combination with serum albumin and BMI." (PMID 38983939, 2024). "Low serum albumin levels also indicate malnutrition in patients." (PMID 39087072, 2024). "Malnutrition, common in hospitalised patients, affects albumin and lymphocyte levels." (PMID 39130833, 2024). "This hypothesis is supported by previous observations that CA125 levels and fibrinogen levels positively correlate with tumor burden, whereas lower albumin levels indicate cachexia along with malnutrition." (PMID 39409916, 2024). "Given the many modalities of assessing malnutrition, a combination of nutritional consults, measurement of body mass and calf circumferences, serum albumin, and quantified food intake could help stratify patients into different risk level groups." (PMID 38541767, 2024). "Malignant tumors are high‐consumption and high‐metabolic diseases that lead to malnutrition, resulting in low serum albumin, total cholesterol levels, and a decrease in raw materials for erythropoiesis such as iron, vitamin B12, and folic acid, thus leading to anemia." (PMID 38562035, 2024). "Depleted serum albumin levels might catalyze muscle atrophy, immunodeficiency, and accentuated malnutrition." (PMID 38761298, 2024). "Although serum albumin concentration is controversial as an index of malnutrition, it can assess general condition, including nutrition, which reflects whether patients can undergo vigorous rehabilitation to improve ADL or not." (PMID 39683392, 2024). "Additionally, a prior investigation has indicated that malnutrition among cancer patients can contribute to a reduction in the synthesis rate of serum albumin, hastening its breakdown and thus leading to hypoproteinemia." (PMID 38169970, 2024). "Low albumin levels are also considered a valid marker of malnutrition." (PMID 39157528, 2024).
malnutrition (continued). "Therefore, albumin, a component of PNI, is important in predicting the risk of amputation in DFUs by predicting malnutrition." (PMID 38611651, 2024). "Serum albumin levels are primarily used to assess malnutrition and chronic diseases." (PMID 38773489, 2024). "The optimal cut-off value of serum GDF15 levels and serum ALB levels for predictive malnutrition in AECOOPD patients was 1,092.885 pg/mL and 36.15 g/L, respectively, with a sensitivity of 65.90 and 86.40%, respectively, as well as specificity of 89.80 and 65.00%, respectively." (PMID 39050134, 2024). "Moreover, the high expression of IL-6 and TNF-α can also lead to a decrease in albumin, a biological indicator of malnutrition in elderly individuals." (PMID 39351234, 2024). "Low albumin levels are widely acknowledged as a reliable marker of malnutrition." (PMID 39003396, 2024). "However, conditions such as malnutrition and malabsorption can also contribute to low albumin levels." (PMID 39368456, 2024). "Consequently, this resulted in low plasma albumin levels and a reduced absolute lymphocyte count, which, according to current understanding, constitutes malnutrition." (PMID 39125277, 2024). "Low serum albumin levels in CKD patients suggest malnutrition." (PMID 39650928, 2024). "Low levels of albumin often suggest malnutrition and weakened immune function in patients." (PMID 39697233, 2024). "Low serum albumin levels is attributed to severe malnutrition associated with TB as well as albumin is a negative acute phase protein, so its concentration decreases in the context of significant inflammation and infection as in TB." (PMID 38982373, 2024). "Therefore, serum GDF15 levels combined with serum albumin levels were used to predict AECOPD malnutrition in patients, and the findings revealed a high sensitivity and specificity, with an AUC of 0.935." (PMID 39050134, 2024). "Furthermore, the malnutrition group exhibited significantly lower levels of specific nutritional indicators, including hemoglobin (p = 0.040), albumin (p = 0.015), and prealbumin (p = 0.021)." (PMID 39850334, 2024). "Furthermore, upon further analysis, it was determined that Karnofsky Performance Status (KPS) score, pain medication use, RBC, WBC, HGB, ALB, PAB, ALT and Urea levels were identified as the primary risk factors for malnutrition in patients diagnosed with CRC." (PMID 39664913, 2024). "ALB is a widely used clinical indicator for malnutrition assessment." (PMID 39050134, 2024). "Furthermore, the Harvey–Bradshaw index directly correlated with malnutrition, while waist circumference and albumin inversely correlated." (PMID 39683376, 2024). "Malnutrition and inflammation can inhibit albumin synthesis, correlating with cancer prognosis." (PMID 39385181, 2024). "The dynamic nature of blood cellular components and albumin levels, which may vary daily in the same patient, and the influence of factors other than systemic inflammation and malnutrition should be considered." (PMID 38896701, 2024). "In addition, we found that lower serum prealbumin and serum albumin increased the incidence of POD, indicating that malnutrition was associated with an increased risk of POD, but there was no cognitive impairment before surgery and postoperative 6-month." (PMID 38694772, 2024). "Although albumin level was not linked to treatment efficacy, it is worth noting that malnutrition is a recognized prognostic indicator for patients with NSCLC, a consensus held by both oncologists and nutrition experts." (PMID 39093502, 2024). "Therefore, albumin was shown to be less useful than prealbumin in predicting malnutrition due to inflammation." (PMID 39619813, 2024). "It is worth noting that although albumin and prealbumin are commonly used biomarkers of malnutrition, their levels can be additionally affected by acute inflammatory stress, which should be considered while interpreting the clinical results by GP practitioners." (PMID 39125381, 2024).
malnutrition (continued). "Nevertheless, a binary logistic regression analysis showed that the serum albumin levels were not an independent risk factor for malnutrition in AECOPD patients." (PMID 39050134, 2024). "Low serum albumin reflects malnutrition and liver and kidney dysfunction." (PMID 38611597, 2024). "First, osteosarcoma, as a wasting disease, may escalate albumin consumption, leading to reduced levels of albumin and subsequent malnutrition, thereby affecting the erythropoietic environment and increasing susceptibility to anemia." (PMID 39621534, 2024). "Vitamin D, calcium, albumin, iron deficiency anemia, sarcopenia, and diagnosed malnutrition have been associated with an increased risk of nonunion in observational studies; however, the literature is highly variable and inconsistent." (PMID 39518692, 2024). "Upon treating the malnutrition, the inflammation may subside, leading to an increase in albumin concentration." (PMID 38319948, 2024). "Hypoalbuminemia due to malnutrition has a poor prognosis, and albumin leakage should be minimized." (PMID 38610630, 2024). "One of the biochemical exponents of increasing malnutrition may be reduced values of albumin concentration." (PMID 39456817, 2024). "In addition, patients with moderate malnutrition had low albumin levels, so it is possible that their BMI remained the same due to the effects of edema." (PMID 38792367, 2024). "The GNRI is computed based on serum albumin and BMI, but it may understate malnutrition in individuals with normal or high BMI." (PMID 39882039, 2024). "In addition, the decreased level of albumin, which is synthesized in the liver, suggests dysfunction in liver synthesis and malnutrition." (PMID 38721021, 2024). "Regarding biochemical parameters, serum albumin tended to be lower in patients with malnutrition (4.2 g/dL vs. 4.4 g/dL, p = 0.07); C-RP was higher in these patients (6.8 vs. 3.7 mg/L; p = 0.05), and 25OHvitD was also lower in this group (13 ng/dL vs. 23 ng/dL, p = 0.02)." (PMID 38794773, 2024). "Malnutrition in these patients was evaluated based on serum albumin levels." (PMID 39519455, 2024). "A lower serum albumin level is thought to be indicative of malnutrition." (PMID 39044193, 2024). "Low albumin levels typically indicate malnutrition and inflammation, which may weaken the immune system and increase the risk of infection and postoperative fever." (PMID 39537756, 2024). "In the future, we may be able to use this platform to detect serum biomarkers, such as GDF15 and ALB to identify malnutrition in patients with AECOPD to provide early nutritional therapy." (PMID 39050134, 2024). "Furthermore, lymphocytes count, hemoglobin, albumin, and cholesterol were all significantly lower in the malnutrition groups (p < 0.05)." (PMID 39872137, 2024). "In addition, albumin levels are a biochemical indicator ofnutritional status, and malnutrition is considered to be one of the factorsassociated with a poor prognosis in seriously ill patients." (PMID 39077353, 2024). "Therefore, it is expected that disorders such as severe malnutrition, cirrhosis, nephrotic syndrome, and other critical illnesses, which lead to reduced levels of plasma albumin, would change the way plasma testosterone is distributed in these individuals." (PMID 39736863, 2024). "Currently used diagnostic methods such as BMI or serum albumin levels are not sufficient to indicate malnutrition, which is affected by many factors, including the number of chronic diseases, multiple medications taken, or physical condition." (PMID 39125381, 2024). "Cholinesterase may reflect malnutrition resulting from decreased dietary intake more precisely than albumin." (PMID 39570570, 2024). "A decreased ALB level could be indicative of malnutrition, which can exacerbate outcomes in patients with COVID-19." (PMID 38303719, 2024). "Patients on dialysis with low serum BChE levels often present with low albumin levels which may be overlooked as malnutrition." (PMID 38420074, 2024).
malnutrition (continued). "ALB levels are considered clinical indicators reflecting malnutrition and chronic diseases." (PMID 39698463, 2024). "Moreover, in this review, several different instruments and tests were used to assess nutritional status, including the MNA (full version), MNA-SF, albumin levels, BMI or the Malnutrition Universal Screening Tool (MUST)." (PMID 39064650, 2024). "While serum albumin is widely used as a diagnostic marker of malnutrition in clinical practice, it should not be used alone, as both inflammation and nutritional risk contribute to low serum albumin levels in acutely ill patients." (PMID 39519527, 2024). "However, since the implementation of neonatal screening, the use of high-calorie diets, management in accredited units, and the introduction of CFTR modulators, there has been a progressive reduction in malnutrition and an improvement in albumin levels." (PMID 39599636, 2024). "The serum albumin to globulin ratio (A/G), determined by dividing serum albumin values by serum globulin values, is an indicator of inflammation and nutrition and is involved in predicting cancer, severe liver disease, malnutrition, and rheumatic disease." (PMID 39539653, 2024). "rOAGB had significantly higher rates of nutritional deficiencies compared to the other two cohorts of this study in calcium, vitamins D and B12, and albumin and hemoglobin levels; however, none of the patients required readmission due to malnutrition." (PMID 38231451, 2024). "ALB plasma concentrations is an indicator of nutritional status and hepatic function, and low preoperative ALB level reflects the malnutrition and anemia of patients before surgery, which might increase the risk of postoperative RBC transfusion." (PMID 36936651, 2023). "Studies have shown that malnutrition and inflammation can inhibit albumin synthesis." (PMID 36924334, 2023). "Since albumin is synthesized in the liver, liver damage, malnutrition, and inflammation may lead to alterations in the rate of albumin synthesis." (PMID 37928538, 2023). "Serum albumin is widely used as a biomarker of nutritional status within patients undergoing surgical operations, with a value of less than 3.5 g/dL used as the standard marker of malnutrition." (PMID 36811703, 2023). "Additionally, patients with malnutrition had lower eGFR, albumin, and lymphocyte levels, accompanied with higher hs-CRP and neutrophil levels." (PMID 38020197, 2023). "Conversely, levels of albumin (Alb), a cellular component weighing 65–70 kDa, may decrease during acute/chronic inflammation and malnutrition." (PMID 37893435, 2023). "Globulin and albumin are made in the liver and are commonly used to evaluate malnutrition." (PMID 36220123, 2023). "In addition, low albumin levels reflect malnutrition due to cancer and negatively impact the prognosis." (PMID 36661734, 2023). "Low serum albumin levels have been included in nutritional predictive models, such as the malnutrition-inflammation score (MIS) and prognostic nutritional index (PNI), both associated with morbidity and mortality in CKD; however, the predictive value of these markers have yet to be fully validated." (PMID 37284646, 2023). "Second, fibrinogen and albumin could be affected by multiple factors, such as concurrent infections and malnutrition, which might influence its reliability as a prognostic marker for futile recanalization." (PMID 37915284, 2023). "Decrease in ALB level is indicative liver damage or malnutrition." (PMID 37950179, 2023). "One of the main roles assigned to albumin is as an indicator of malnutrition." (PMID 37735699, 2023). "Albumin has been used as an indication of malnutrition in medically stable individuals for decades." (PMID 36771359, 2023). "In acute and chronic illness, serum albumin may decrease as a result of a transcapillary leak, impaired synthesis related to liver dysfunction, malnutrition, or inflammation." (PMID 37108536, 2023).
malnutrition (continued). "In all patients with UGIB, the required dietary control may lead to malnutrition, as reflected by a low ALB level." (PMID 37715244, 2023). "Since albumin is seen as a marker for nutritional status and inflammation, a low albumin level may indicate malnutrition, chronic hepatitis, nephrotic syndrome or an inflammation status." (PMID 36864383, 2023). "Accordingly, the relationship between ALB and malnutrition warrants further exploration." (PMID 37715131, 2023). "The serum albumin level has been used for the diagnosis of protein–energy malnutrition and malnutrition (evaluated by mini nutritional assessment and BMI); the serum albumin level is strongly associated with oropharyngeal dysphagia in older patients hospitalized for an acute disease." (PMID 37762776, 2023). "Reduced albumin levels are correlated with malnutrition and systemic inflammation." (PMID 36875097, 2023). "Albumin is a biomarker of malnutrition and frailty in older patients." (PMID 37181348, 2023). "Moreover, a combination of anthropometric measurements (e.g., BMI), biochemical markers (e.g., albumin), and tools such as the Malnutrition Universal Screening Tool (MUST) are used for identifying malnutrition." (PMID 38131687, 2023). "The main pathological mechanisms of malnutrition in AKI patients are the reduced intake of nutrients and the loss of protein and energy related to metabolic disorders, which lead to a decrease in BMI and albumin." (PMID 37250638, 2023). "Prealbumin, as a marker of recent malnutrition, may complement the information provided by albumin, a well-established prognostic factor in older patients with DLBCL." (PMID 37058153, 2023). "Multivariate analysis confirmed that baseline malnutrition (p = 0.004) and VAS score for appetite loss (p = 0.0104), in addition to albumin < 35 g/L (p < 0.0001) and neutrophil/lymphocyte ratio > 3 (p = 0.0007), were independently associated with the death of non-metastatic patients at follow-up." (PMID 37370816, 2023). "This could be related to the average age of our sample, close to 70 years, as well as the inclusion of other markers of malnutrition, such as albumin." (PMID 38201844, 2023). "Malnutrition, routinely indicated by low serum albumin, often coexists with sarcopenia and may accelerate the muscular degeneration process." (PMID 37762867, 2023). "However, the total level of both biomarkers, serum urea and albumin, is affected by various factors, e.g., hypovolemia, trauma, malnutrition, cancer, and catabolism as well as hepatic or renal insufficiency." (PMID 37240644, 2023). "In a cancer patient, several factors can affect serum albumin and total protein concentrations, such as malnutrition, cachexia, tumor necrosis, chemotherapy-induced hepatotoxicity, and inflammatory states, making the understanding of protein metabolism more challenging." (PMID 37390617, 2023). "Multivariate analysis confirmed that baseline malnutrition (p = 0.004) and VAS score for appetite loss (p = 0.0104), in addition to albumin < 35 g/L (p < 0.0001) and neutrophil/lymphocyte ratio >3 (p = 0.0007) were independently associated with death of non-metastatic patients at follow-up." (PMID 37370816, 2023). "ALB (Serum albumin) has been widely used as an indicator of malnutrition in the clinical setting." (PMID 37714898, 2023). "The possible explanation could be in cancer related malnutrition, nutrient deprivation and inflammation, downregulates serum albumin gene expression leading to inhibition of synthesis." (PMID 36869395, 2023). "A slight decline in the albumin level might reflect some condition, including the presence of decreased liver synthesis, chronic inflammation, and malnutrition." (PMID 36766578, 2023).